TNF (tumor necrosis factor)
Diseases named in the same sentence as TNF in open-access papers (continued):
Sharing a sentence is not in itself a finding about the gene and the disease.
cancer (continued). "In other studies in patients with cancer, associations have been shown between appetite loss and IL-1β, IL-6 and IL-8 and with gene polymorphisms coding for TNF-α, IL-1β, and IL-10." (PMID 28542626, 2017). "S100A6 expression has been associated with protection from TNF-α-induced apoptosis in cardiomyocytes, decreased metastasis rate in cancer of the bone, as well as the regulation of cell cycle progression." (PMID 28206967, 2017). "Cancer‐associated chronic inflammation upregulates the production of inflammatory cytokines, such as (IL, interleukin) IL‐6, TNF‐α (tumor necrosis factor,TNF), and IL‐1β1." (PMID 26880719, 2016). "To explore a more precise estimation of the relationship between TNF-α T-857C polymorphism and cancers, we performed a meta-analysis." (PMID 28115787, 2016). "Misregulation of TNF signaling has been attributed as a major cause of chronic inflammatory diseases and cancer." (PMID 27671354, 2016). "Available studies show that TNF-α induces the expression of MCP-1 in cancer-associated fibroblasts and mesenchymal stem cells by up-regulating the nuclear factor-κB (NF- κB) pathway." (PMID 27028862, 2016). "In our meta-analysis, we aggregated data from published studies to estimate genetic associations between the TNF-α T-857C polymorphism and the susceptibility of five common cancers." (PMID 28115787, 2016). "Some studies have found associations between heightened levels and increased risk of some cancers as well as evidence that TNF-α is involved in tumorigenesis including cellular transformation, angiogenesis and metastasis." (PMID 27170831, 2016). "There are a large number of studies on the association between TNF-α G-308A (rs1800629), TNF-α G-238A (rs361525), and cancers; TNF-α G-308A (rs1800629) and TNF-α G-238A (rs361525) have been successfully identified as risk factors of cancer." (PMID 28115787, 2016). "TNF was recently shown to hamper alternative activation of macrophages in murine models of cancer by suppressing Th2-associated cytokine expression." (PMID 27849167, 2016). "It is interesting to note that constitutive TNFα production has previously been linked to sensitivity of human cancer cell lines towards Smac mimetics." (PMID 27385100, 2016). "Dysregulated activity of A Disintegrin And Metalloproteinase 17 (ADAM17)/TNFα Converting Enzyme (TACE) is associated with inflammatory disorders and cancer progression by releasing regulatory membrane-tethered proteins like TNFα, IL6R and EGFR ligands." (PMID 27982031, 2016). "Tumor necrosis factor (TNF)-α and TNFR-1 mRNA were shown to be elevated in several animal models of cancer cachexia and pharmacological inhibition of TNF-α showed a reduction in weight loss due to cancer in rodents." (PMID 26856534, 2016). "The controversial association between TNF-α-308 G/A polymorphism and cancer still needs to be confirmed." (PMID 27821804, 2016). "Abnormal in the expression of TNF has been identified to be associated with major depression, Alzheimer's disease, psoriasis, inflammatory bowel disease and cancer." (PMID 27821804, 2016). "A previous study revealed that 5-episinuleptolide caused the inhibition of TNF-α and nitric oxide production in macrophages from several cancer cell lines, indicating an effect of the immune system." (PMID 27483290, 2016). "In this study, we show that repetitive oral administration of XAT decoction for a week can greatly suppress the increased IL-1β and TNF-α associated with the cancer pain." (PMID 26617438, 2015). "The canonical pathway is most usually associated with cancer, and is mainly activated by TNF-α, IL-1, and LPS." (PMID 26203774, 2015). "Nonetheless, TNFα is a valuable protective mechanism, as TNFα inhibitor therapy in humans is associated with increased risk of infections and, significantly, cancer." (PMID 25948885, 2015).
cancer (continued). "In the present study, we found on a subset of samples where RNA were available, that the CC variant of rs2853669 is associated with an increased expression of IL-6 and TNFα, cytokines considered as markers for inflammation and cancer progression." (PMID 26298771, 2015). "TTP negatively regulates cell growth in several cancer cell types by inhibiting the stability of many mRNA implicated in cell cycle (c-Myc, cyclin D1), inflammation (TNFα, COX-2), apoptosis (Bcl-2, Mcl-1), and angiogenesis (VEGF)." (PMID 26343742, 2015). "The proinflammatory cytokines, including TNF-α, IL-6, and IL-1β have been regarded as crucial factors causing cancer cachexia and muscle atrophy." (PMID 26600425, 2015). "The neighboring DARPP-32 gene codes for a Dopamine and cAMP-regulated phosphoprotein, and its over-expression has been implicated in resistance to tumor necrosis factor (TNF)-related apoptosis-inducing ligand (TRAIL) receptor targeted therapy in cancer." (PMID 25906114, 2015). "Although, all of these 3 signaling pathways are actively associated with cancers, as describing above, only the TNF signaling pathway is extensively involved in both the early and late recurrence/metastasis of H-HCC." (PMID 24839399, 2014). "And overexpression of HER-2/neu induces resistance to TNF, which causes cancer cells to escape from host immune defenses." (PMID 25034939, 2014). "Pro-inflammatory cytokines, such as TNF-α, IL-1, and IL-6, have been implicated in the development of cancer cachexia and have been shown to exhibit synergistic effects." (PMID 24624094, 2014). "Systematic review and meta-analyses of clinical trial data have revealed an increased short-term risk of certain cancers in patients taking TNF inhibitors." (PMID 25267341, 2014). "Selective inhibition of NFκB in cancer cells blocks the stimulatory effect of TNF and markedly increases susceptibility to TRAIL-induced cell death, resulting in tumor regression." (PMID 25132836, 2014). "TNF-α-mediated inflammation has been linked to cancer; for instance, increased TNF-α levels in preneoplastic lesions have been detected in H. pylori-positive gastric lesions, through H. pylori-secreted TNF-α-inducing protein (Tipα)." (PMID 24901008, 2014). "Nonetheless, our study provides important evidence of the safety, in terms of cancer risk, of anti-TNF-α antagonists in RA patients who survive long-term disease and who undergo long-term DMARD treatment." (PMID 25267341, 2014). "The risk of newly diagnosed cancer was compared between patients starting TNF-α antagonists (biologics cohort) and matched subjects taking nbDMARDs only (nbDMARDs cohort)." (PMID 25267341, 2014). "The current study suggested that the addition of anti-TNF-α therapy is safe, in terms of cancer risk, for RA patients undergoing long-term DMARD treatment, based on a Taiwanese nationwide population." (PMID 25267341, 2014). "It is also interesting to note that loss of WAVE3 can sensitize cancer cells to TNFα-induced apoptosis and cell death." (PMID 25329315, 2014). "Many factors have been implicated in cancer cachexia including cytokines (TNFα, IL-6), ZAG and myostatin." (PMID 24667661, 2014). "TNF-α production has been implicated in a variety of other human pathologies including neurodegeneration and cancer." (PMID 25336399, 2014). "Recently, TNF-a 308 polymorphism was confirmed as a risk factor for a range of cancers by meta-analysis, such as gastric, breast and hepatocellular cancers." (PMID 24404201, 2014). "Several drugs currently used in clinic against IBDs, such as azathioprine and anti-TNFα, have prompted considerable concern about an increased risk of developing cancer when they are used on a long-term basis." (PMID 24616647, 2014). "Tumor necrosis factor is associated with multiple functions in cancer biology, including cancer cell survival, angiogenesis, migration and invasion." (PMID 25072850, 2014).
cancer (continued). "Our study identifies another important function of WAVE3 in the NFκB pathway that is also independent from the other WAVE isoforms; i.e., loss of WAVE3 sensitizes cancer cells to apoptosis and ultimately cell death after stimulation by TNFα." (PMID 25329315, 2014). "TNFα is a well known pro-inflammatory cytokine and has in most cases been linked to reduced proliferation of cancer cell lines." (PMID 24296981, 2014). "Loss of WAVE3 also sensitized cancer cells to apoptosis and cell death driven by TNFα, through the inhibition of the AKT pro-survival pathway." (PMID 25329315, 2014). "Myofibroblasts are a target of inflammatory mediator signaling and, in particular, TNF-α, a 17-kDa pro-inflammatory cytokine that has been implicated in the pathogenesis of colitis-associated cancer." (PMID 23688423, 2013). "We discuss the effect on cancer risk of different drug classes used in the treatment of IMIDs treatment, including biologicals such as tumor necrosis factor (TNF) inhibitors." (PMID 23987103, 2013). "Deregulation of TNF-α is implicated in wide spectrum of diseases like diabetes, osteoporosis, autoimmune diseases and cancers." (PMID 24324738, 2013). "Thiopurines increase the risk for NMSC, while limited data are available on the effect of anti-TNF treatment on cancer risk in IBD." (PMID 23987103, 2013). "NFκB was identified as a potential central upstream regulator implicated in the TNF-α signaling that plays important roles in inflammation, tissue remodeling and cancer development." (PMID 24133572, 2013). "The present repotted pictogram quantities of TNF-α are also produced by the malignant cell of advanced cancer its presence often being associated with poor prognostic factors." (PMID 24459422, 2013). "Pro-inflammatory cytokine TNFα can induce cancer invasion and metastasis associated with epithelial–mesenchymal transition (EMT)." (PMID 23431386, 2013). "Deficiency of TIA-1 in cancer cells is associated with elevated levels of tumor necrosis factor-α (TNF-α) and COX-2." (PMID 23975167, 2013). "An increase of circulating TNF-α levels has been associated with significant fatigue in cholestatic patients with cancer." (PMID 23710202, 2013). "Apprehensions about cancer were common, and many considered themselves at ongoing risk while they were taking anti-TNF." (PMID 23663548, 2013). "Molecular analyzes in epidermal fibroblasts demonstrated disturbances to the expression profile of core circadian clock genes and elevated expression of the proinflammatory cytokines IL-6 and TNF-α, known to be risk factors in cancer and metabolic disorders." (PMID 24146819, 2013). "Inflammatory factors such as TNF-α are thought to be major causes of elevated NF-κB in cancer cells." (PMID 24386633, 2013). "By microarray analysis, we have identified a genetic signature that responds to TNFα in a 14-3-3σ-dependent manner and significantly associates with different breast and other types of cancer." (PMID 22675457, 2012). "For example, TNF-α and IL-1β secreted from macrophages are not only essential in initiation of chronic inflammation, but also associated with the initiation of cancer by activating NF-κB signal pathway." (PMID 23227270, 2012). "This would subsequently lead to the release of other cytokines (e.g. TNF), causing chronic inflammation and cancer." (PMID 23239971, 2012). "At this regard, several studies showed an association between elevated circulating TNF-α levels and cancer development stimulating cell proliferation, causing DNA damage and promoting angiogenesis." (PMID 23133455, 2012). "Previously published MAs assessing cancer risk on anti-TNF-α have been conducted in intention to treat analysis or modified intention to treat analysis (mITT)." (PMID 23155441, 2012).
cancer (continued). "As the number of drops out is much higher in placebo arms than in anti-TNF-α arms (loss to follow-up or dropping out for inefficacy), this would result in overestimation of the cancer risk on anti-TNF-α therapy." (PMID 23155441, 2012). "One of the key mediators implicated in inflammation-associated cancer is tumor necrosis factor alpha (TNFα)." (PMID 22675434, 2012). "A total of 34 studies were identified to evaluate the relationship between TNF-α-238 polymorphism and risk for cancer." (PMID 21818296, 2011). "TNF-α-308 polymorphism has been confirmed as a risk factor for a range of cancers by meta-analysis, such as breast, gastric and hepatocellular cancers." (PMID 21818296, 2011). "Evidences suggest that BRCA1 part of the "Role of BRCA1, BRCA2 and ATR in Cancer Susceptibility" pathway significantly enhances the ability of TNF-α or IFN-γ to activate transcription from the promoters of NF-κB target genes." (PMID 21226955, 2011). "Because A allele of TNF-α at −238 in the promoter region was found to down-regulate gene expression, studies on the relationship between this variant and cancers has been extensively investigated during recent decades." (PMID 21818296, 2011). "The keywords were as follows: cancer/carcinoma, polymorphism/variant/genotype/SNP, and tumor necrosis factor/TNF-α." (PMID 21818296, 2011). "The study incorporates comprehensive surveillance for cancer detection because of the increase risk of malignancy in patients treated with TNF-α antagonists." (PMID 21310077, 2011). "Several potential factors must be concerned with respects to the null association between TNF-α-238 polymorphism and cancers." (PMID 21818296, 2011). "Aberrant NF-κB activity in cancer cells is implicated in apoptosis resistance to various stimuli, including inflammatory cytokines like TNF-α." (PMID 21880146, 2011). "The OR for cancers (95% CI) in overall studies with AA+AG vs GG of TNF-α-238 polymorphism was 1.09 (0.88–134, P = 0.42) (Table." (PMID 21818296, 2011). "In this article, the association of TNF-α-238, −308 with cancer risk was investigated using meta-analysis in a range of populations." (PMID 21818296, 2011). "When administered in combination with other neutraceuticals, andrographolide caused an increase in function of NK cells and TNF-α thus resulting in improved clinical outcomes in patients with late stage cancers of different types." (PMID 19752167, 2011). "Some TNF-α polymorphisms have been confirmed to increase cancer risks; however, the association between TNF-α-238 polymorphism and cancers remains controversial and ambiguous." (PMID 21818296, 2011). "Electronic databases (PubMed, EMBase, Cochrane Central Register of Controlled Trials and ISI Web of Science) were searched for all publications on the association between TNF-α-238 polymorphism and cancer through March 2011." (PMID 21818296, 2011). "To the best of our knowledge, we used meta-analysis to investigate the association between TNF-α-238 polymorphism and risk of cancers for the first time." (PMID 21818296, 2011). "More recently, given that cancer progression is preceded by a long period of subclinical inflammation, the genetic polymorphisms of TNF-α, TNFRSF1A and TNFRSF1B have been examined in terms of susceptibility to various cancers." (PMID 20646319, 2010). "Apart from the production of myeloid growth factors, cancer inflammation and associated neutrophilia have also been associated with the release of IL-6 (interleukin-6) and TNF-α (Tumour necrosis factor-α)." (PMID 20053279, 2010). "Activation of TNF-α/NF-κB pathway has been shown to contribute to inflammation-associated cancer such as hepatitis-related HCC." (PMID 20356387, 2010). "Conversely, anti-TNF therapy has been suggested as a possible treatment for cancer-associated cachexia." (PMID 20535785, 2010).
cancer (continued). "Overexpressing Par-4 can increase susceptibility of cancer cells to apoptotic agents such as doxorubicin, tumor necrosis factor alpha (TNF-α), and tumor necrosis factor-related apoptosis-inducing ligand (TRAIL)." (PMID 20433755, 2010). "One of the key chemical mediators implicated in inflammation-associated cancers is TNF-α, and there is now substantial evidence in its involvement in promotion and progression of experimental and human cancers." (PMID 20699000, 2010). "Elevated levels of TNFα are linked to a poor prognosis and increased invasiveness in certain human cancers." (PMID 20064207, 2010). "Expression of MMP-2, MMP-9 and TNF-α is strongly linked with malignant tumor progression, angiogenesis and metastasis of various types of cancers." (PMID 20573279, 2010). "In contrast to an increased risk, it is also possible that inhibition of TNFα has beneficial or even preventive effects regarding cancer." (PMID 20064207, 2010). "Egr-1 (Early growth response 1) is a transcription factor that acts in apoptosis, angiogenesis, cell differentiation, regulates TNF production, cell proliferation and adhesion and aberrant expression of the gene is associated with several types of cancer." (PMID 19604364, 2009). "A second network related to cancer and cellular development linked 17 members of this signature to tumor necrosis factor (TNF)-α and estrogen." (PMID 18631401, 2008). "Cytokines, particularly TNF-α, IL-6, and interferon-γ, have been suggested to be responsible for the metabolic changes associated with tissue loss in cancer wasting." (PMID 18226207, 2008). "Increased production of the proinflammatory cytokine TNFα has been implicated in a number of human diseases involving inflammation such as autoimmune disorders, vascular disease and a number of cancers." (PMID 18070349, 2007). "From these results, we propose that TNFα expression or PI3-kinase activation lead to reduced levels of ERα protein in cancer cells and corresponding loss of transrepression function and acquisition of an invasive phenotype." (PMID 14970864, 2004). "TNF-α is a pleiotropic cytokine, which like IL-6 has been shown to be associated with cancer progression." (PMID 15150588, 2004). "It is concluded that weight loss produced by TNF-alpha arises from an anorexic effect and that this differs from the complex metabolic changes associated with cancer cachexia." (PMID 3390373, 1988). "Pro-inflammatory cytokines like interleukin-6 (IL-6) and tumor necrosis factor-alpha (TNF-α) have been implicated in cancer progression and may influence CRC outcomes." (PMID 41792766, 2026). "Muscle loss may exacerbate cancer-related inflammation, elevated inflammatory factors such as interleukin-6 and tumor necrosis factor-α may lead to immunosuppression." (PMID 40904512, 2025). "In addition to alterations in adiponectin and leptin levels, elevated levels of other adipokines, such as resistin, interleukin‐6 (IL‐6), and tumor necrosis factor‐alpha (TNF‐α), are associated with an increased risk of cancer." (PMID 40620232, 2025). "This underscores the role of TNF‐α in skeletal muscle depletion associated with cancer cachexia." (PMID 39764565, 2025). "Therefore, future research should focus on modulating the associated pathways and altering the response to TNF‐α to develop therapeutic strategies for cancer cachexia." (PMID 39764565, 2025). "Moreover, it is verified that TNF-α polymorphism is a risk factor for several different cancers, including gastric, liver, and breast cancers." (PMID 41305639, 2025). "IL1B, TNF, etc., were associated with inflammation and cancer-related pathways." (PMID 41155650, 2025).